BMI1 (BMI1 proto-oncogene, polycomb ring finger)
Diseases named in the same sentence as BMI1 in open-access papers (continued):
Sharing a sentence is not in itself a finding about the gene and the disease.
cancer (continued). "High expression of BMI‐1 in cancer was related to epithelial–mesenchymal transition (EMT) and poor prognosis." (PMID 32588101, 2021). "Although some of the studies found that miR-135 acts as an antioncogene in several cancers including OS, and this is the first report that miR-135a can inhibit OS development by targeting BMI1 and KLF4 in vitro and in vivo." (PMID 33828977, 2021). "The downregulation of Bmi1 inhibits tumor cell growth in different cancer types, and siRNA can downregulate the expression of oncogenes." (PMID 34295253, 2021). "Not only are CSCs resistant to therapy, but cytotoxic agents actually enhance cancer stemness by activating transcription of pluripotency factors and by inducing expression of Bmi-1, a master regulator of stem cell self-renewal." (PMID 34689150, 2021). "The emergence and testing of new BMI1 inhibitors for the treatment of cancer suggest that BMI1 is a relevant target for cancer therapy." (PMID 32343689, 2020). "BMI1 was a significantly rewired TF and maintained edges with 14 other factors, including a well-known cancer-related histone modification mark H3K27me3." (PMID 32615918, 2020). "Using GSEA, we found that genes upregulated in response to BMI1 knockdown in cancer cells were also upregulated in PTC596 and A1016-treated GBM cells, suggesting efficient drug-mediated BMI1 inhibition." (PMID 31934644, 2020). "BMI1 is a core protein of the polycomb repressive complex 1 (PRC1) that is overexpressed in several cancer types, making it a promising target for cancer therapies." (PMID 32343689, 2020). "By contrast, regulation of BMI1 with inhibitors or short hairpin RNAs (shRNAs) results in cellular senescence or apoptosis of several types of cancer cells and sensitizes tumor cells to cytotoxic agents or radiation." (PMID 32343689, 2020). "The oncogenic polycomb group protein Bmi-1 regulates both normal and cancer stem cells in multiple tissues." (PMID 33584271, 2020). "Background and objectives: B-lymphoma Mo-MLV insertion region 1 (Bmi-1) is a stem cell factor that is overexpressed in various human cancer tissues." (PMID 32059385, 2020). "It was reported that BMI1 can activate Wnt pathway, and Wnt/β‐catenin pathway was extensively supported as a contributing signaling for cancer cell growth, stemness, and EMT." (PMID 32239639, 2020). "In other cancers, BMI-1 suppresses the tumor suppressor gene p19ARF, thus counteracting its overexpression induced by c-MYC." (PMID 33126754, 2020). "We also observed the decreased expression of several cancer stemness genes, including BMI1, Oct4, and Sox2, which maintain breast CSCs 27-29." (PMID 32922184, 2020). "We show that reduction of BMI1 levels by shRNA or inhibition with the small molecule inhibitor PTC-318 significantly reduced cell viability of different cancer cell lines." (PMID 32343689, 2020). "Bmi1, a member of the Polycomb Repressor Complex 1, is a crucial regulator of the self-renewal and malignant transformation of many cancers." (PMID 32850313, 2020). "In agreement with this, SOX9 expression positively correlated with BMI1 levels and inversely with p21CIP in clinical samples of the different cancers." (PMID 31941916, 2020). "Encouraged by the therapeutic potential of BMI1 inhibition, we assessed the effect of PTC-318, a new and previously unpublished small molecule inhibitor of BMI1, on human cancer cells and evaluated its underlying mechanisms of action." (PMID 32343689, 2020). "The expression of BMI‐1 was also lower in cancers that exhibited the ability to metastasize to regional lymph nodes compared to non‐metastatic cancers." (PMID 31863623, 2020). "Aberrant BMI1 expression contributes to the maintenance of CSC subpopulations in multiple types of cancer." (PMID 32987767, 2020). "This indicates that BMI1 re-establishes the proliferative capacity of cancer cells abrogated by SOX9 knockdown." (PMID 31941916, 2020).
cancer (continued). "BMI-1 is upregulated in multiple cancers where it promotes the CSC phenotype and correlates with poor prognosis." (PMID 32507861, 2020). "BMI1 has been reported to be a positive regulator that induces the stem cell-like properties of cancer cells." (PMID 32005118, 2020). "B cell-specific Moloney murine leukemia virus integration site 1 (BMI1) is suggested to undergo upregulation in different cancers." (PMID 32784711, 2020). "BMI1 overexpression is a well-established inducer of cancer cell proliferation and resistance to cancer drug treatments of various cancer cell lines, highlighting the potential of specific BMI1 inhibitors." (PMID 32343689, 2020). "BMI1 has been recognized as a positive regulator that induces cancer stem cell-like properties, which are deeply involved in irinotecan resistance." (PMID 32799866, 2020). "Analysis revealed that genes associated with cancer stem cells, such as POU5F1 (OCT4), SOX2, NANOG, BMI1, BMP2, CD44, SOX9, and ALDH1 were markedly upregulated in enzalutamide resistant cells." (PMID 33339129, 2020). "Mechanistically, the modulation of SOX9 changed the expression of the transcriptional repressor BMI1 in the same direction in the three types of cancer, and the expression of the tumor suppressor p21CIP in the opposite direction." (PMID 31941916, 2020). "In this work, we found that modulation of SOX9 levels affects BMI1 expression in multiple cancer cell lines in vitro and in vivo." (PMID 31941916, 2020). "Owing to the important roles of EZH2 and BMI1 in epigenetic regulation, they are often overexpressed in cancer cells and are required for self-renewal of stem cells." (PMID 33168810, 2020). "The expression of ALDH1A1, a CSC marker, and the cancer stemness factors including BMI1, NANOG, and octamer-binding transcription factor (OCT4) were also reduced in both AN3CA and HEC1A cells after TRIB3 silencing." (PMID 33334065, 2020). "Although BMI1 has been explored rigorously in the context of various cancers, we have only begun to investigate the link between BMI1 and LOAD." (PMID 32708145, 2020). "B lymphoma Mo-MLV insertion region 1 homolog (BMI1) is a protein of the polycomb group involved in epigenetic regulation and overexpressed in many cancer types including breast." (PMID 33015128, 2020). "The knockdown of TRIB3 in EC cells causes a reduction in cell proliferation, migration, invasion, CSC activity, and in vivo tumor formation through the inhibition of cancer stemness genes, such as BMI1, OCT4, Nanog, β-catenin, and c-MYC." (PMID 33334065, 2020). "Some minor differences in transcriptional regulations on cancer stemness were found, such as Slug and Snail1 were enhanced only by Q311E, whereas Bmi1 was upregulated by WT‐MB21D2." (PMID 32979859, 2020). "Mechanistically, SOX9 exerts these pro-tumoral actions through BMI1- p21CIP, providing novel knowledge regarding the molecular events leading to cancer progression." (PMID 31941916, 2020). "BMI1 overexpression ensures tumor sphere formation of cancer cells, and its stability is a positive factor for tumorigenesis." (PMID 32784711, 2020). "Noteworthy, the heatmap representation revealed that the expression of SOX9 correlated positively with BMI1 expression and negatively with p21CIP in samples from the different types of cancer." (PMID 31941916, 2020). "Bmi-1 levels were significantly higher in carcinoma (G1–G3) than in the secretory phase; similarly, Ki-67 expression was significantly higher in G3 than in the secretory phase." (PMID 32059385, 2020). "Recently, researchers have found that BMI-1 oncogene-driven pathway plays an important part in tumor development and metastases, and BMI-1 overexpression has been demonstrated in many carcinomas." (PMID 33302959, 2020). "USP22 knockdown reduces the invasiveness and metastasis of multiple cancers by downregulating pathways driven by the oncoprotein, BMI-1." (PMID 31689236, 2019).
cancer (continued). "The oncogenic roles and pathological relevance of Bmi1 in human cancers have attracted considerable attention." (PMID 30918246, 2019). "Despite the critical role of UA or Bmi1 siRNA in cancer treatment individually, the use of nanocarrier to co-deliver both of them as a combination therapy has not been reported." (PMID 31366257, 2019). "Among these cancer stem cell-related proteins, β-Asarone induced suppression of Bmi1 expression was more obvious than others." (PMID 31171917, 2019). "Accumulating evidence has demonstrated that Bmi1 is also involved in the regulation of self-renewal, differentiation, and cancer stem cells properties." (PMID 31171917, 2019). "Bmi1 also plays an essential role in the regulation of endogenous stem cells and cancer stem cells function." (PMID 31171917, 2019). "Increasing evidence has demonstrated that Bmi1 is highly expressed and involved in the pathogenesis of various aggressive cancers, including breast, neuroblast, colon, and esophagus." (PMID 30679589, 2019). "In cancer, the polycomb protein BMI1, in cooperation with MYC, promotes tumor development by repressing tumor-suppressor genes, such as INK4A and ARF." (PMID 33912356, 2019). "Our finding from current study is concordant with our previous data implicating BMI1 in protecting cancer cells from radiation therapy-induced apoptosis." (PMID 31548560, 2019). "Bmi1 also affected the occurrence and development of several types of cancer due to its influence on cancer stem cell-like phenotype." (PMID 31366257, 2019). "Recently, it was reported that IL-1β regulates cell proliferation through stemness markers such as Bmi-1, Lgr-5, c-myc and Nanog in cancer stem cells." (PMID 31671670, 2019). "The western blot measurement of apoptosis-protein and cancer stem cell (CSC) marked-protein demonstrated that UA led to activation-induced tumor cell death and Bmi1 siRNA resulted in inhibition of cancer stem cells." (PMID 31366257, 2019). "YY1 has been associated with a regulatory loop with cancer stem cell transcription factors (SOX2, OCT4, BMI1) during the cross-talk between the NF-kB/PI3K/AKT pathways." (PMID 31867044, 2019). "The stabilized BMI1 complex then regulates its target genes to promote malignant behaviors and stemness of cancer cells." (PMID 31138311, 2019). "Twist is a versatile CSC regulator, which on the one hand activates the CSC self-renewal by upregulating Bmi1 expression and on the other hand, induces the reprogramming of fully differentiated cancer cells into CSC state through EMT." (PMID 30918246, 2019). "We determined the protein levels of BMI-1 in different cancer cells and normal cells by western blotting." (PMID 31640758, 2019). "We noticed that β-Asarone treatment significantly suppressed the expression of cancer stem cell-related proteins (c-Myc and Bmi1) in a dose-dependent manner." (PMID 31171917, 2019). "Although it has been widely reported that PTC-209 exerts its activity through downregulation of Bmi-1 protein level in various types of cancer cells, there are still controversy regarding the exact mechanism through which it downregulates Bmi-1." (PMID 31695609, 2019). "Abnormal expression of Bmi1 was seen in a variety of cancers, and was related to malignant behaviors of cancer." (PMID 31088566, 2019). "Our study provides the preclinical evaluation of the effect of targeting BMI-1 on cancer treatment in vitro and in vivo." (PMID 31640758, 2019). "Recent studies reported that genetic or pharmacological inhibition of BMI-1 induced autophagy in cancer cells." (PMID 31640758, 2019). "Overexpression of BMI-1 is closely related with tumor progression by the involvement in tumor initiation, metastasis, invasion and chemoresistance within various cancer types." (PMID 31640758, 2019).
cancer (continued). "The expression levels of BMI-1 were lower in normal cells compared to cancer cells, which was consistent with the result that QW24 has lower toxicity to normal cells." (PMID 31640758, 2019). "Overexpression of the other four (SOX2, POU3F2, OCT-4, and OLIG1) or five (SOX2, SALL2, OCT-4, POU3F2, and Bmi-1) transcription factors in YB-1 knockout cancer stem cells generated similar results." (PMID 31375149, 2019). "We subsequently extended our investigations to the HCT116 (colon) and PC-3 (prostate) cancer models, since those two models are known to harbor BMI1+ CSC populations." (PMID 31548560, 2019). "In leukemic cells, BMI1 promotes cancer cell self-renewal via H2AK119ub1-mediated repression of key tumor suppressor genes, including the INK4A/ARF locus." (PMID 30781493, 2019). "A Zeb1lo, CD44lo, E-Cadherin+, Zeb2−, Pten−, pS473Akt+, Bmi1+, nuclear Yap1+ pattern was maintained in cancer cells as they divided symmetrically to form papillary tumors." (PMID 29930325, 2018). "We observed that 1794 genes were upregulated, while 1897 genes were downregulated by knockdown of BMI1, suggesting that BMI1 functions as a transcriptional activator along with its well-known transcriptional repression role in cancer." (PMID 29402932, 2018). "BMI-1 has been indicated to be involved in the protection of cancer cells from apoptosis or drug resistance in various types of cancer, including nasopharyngeal carcinoma, melanoma, pancreatic adenocarcinoma, ovarian cancer, and hepatocellular carcinoma." (PMID 29681949, 2018). "BMI1, a polycomb group (PcG) protein, plays a critical role in epigenetic regulation of cell differentiation and proliferation, and cancer stem cell self-renewal." (PMID 29402932, 2018). "More importantly, accumulating genetic and epigenetic evidence has revealed BMI1, serving as a cancer stem cell marker, plays a crucial role in tumor heterogeneity and relapse." (PMID 29685168, 2018). "A growing number of recent studies have confirmed the oncogenic activation of BMI1 in diverse human malignancies and have explored the function of BMI1 as a pathway regulator in both stem cells and cancer cells." (PMID 29685168, 2018). "ZEB2 acts as a transcriptional repressor of E-cadherin and increases invasion, and high levels of BMI1 is correlated with EMT characteristics in cancer cells." (PMID 30463333, 2018). "Our finding was further supported by western blotting, which showed that expression of cancer stem markers, Bmi1, Sox2 and Musashi1, was markedly increased by treatment with TGF-β1 and decreased by treatment with metformin." (PMID 29467947, 2018). "And as the key downstream effectors of OPN for cancer stemness, the expression levels of BMI1 and HIF1α were increased when DNMT1 was up-regulated in CD133+/CD44+ cells with shOPN." (PMID 30064482, 2018). "Bmi-1 protein was up regulated to a much greater extent than Bmi-1 mRNA in cancer tissue, suggesting deregulation at the post-transcriptional level despite that some authors reported no significant Bmi-1 mRNA expression." (PMID 30072631, 2018). "The enzymatic subunit or “writer” of PRC1, BMI-1, is considered to play a role in malignant transformation of multiple cancers, including ovarian cancer." (PMID 30478317, 2018). "Numerous studies have demonstrated that BMI1, which is upregulated in a variety of cancers, has a positive correlation with clinical grade/stage and poor prognosis." (PMID 29212025, 2017). "Bmi1 has been shown to be upregulated in cancers, including OVCA, but its role in ovarian CSC expansion has not been established." (PMID 28179359, 2017). "Several target genes including p16 and E-cadherin have been identified to be responsible for these essential oncogenic roles of Bmi1 in diverse cancer contexts including HNSCC." (PMID 29200967, 2017).
cancer (continued). "Transcriptional profiling data of human cancer in GENT revealed that the mRNA level of Bmi1 varied remarkably among diverse human cancers and its abundance was frequently higher in cancers than those normal counterparts including HNSCC." (PMID 29200967, 2017). "Functional implications of the BMI1/CK2α axis was examined in cancer cells utilizing siRNA and exogenous gene expression followed by biochemical and phenotypic studies." (PMID 28270146, 2017). "Abnormal overexpression of Bmi-1 has also been proposed to be involved in tumor invasion, metastasis, cancer therapy failure, and poor prognosis." (PMID 28122538, 2017). "For this reason, it seems unlikely that the induction of CDKN2A and CDKN2B expression observed in both these cancers is related to a reduction in expression of the BMI1 component of PRC1." (PMID 29069809, 2017). "Apart from induction of EMT and cancer cell stemness, growing evidence suggests that tumor recurrence and chemoresistance of CSCs are in part due to the activation of Bmi1." (PMID 27926533, 2017). "Recently, the development of PTC-209, a small specific inhibitor of BMI-1, has opened new avenues to evaluate the therapeutic potential of BMI-1 in cancer including MM." (PMID 29262596, 2017). "If human cancer cells with rainbow construct would be available, in vitro lineage-tracing using these must be helpful to investigate the manner how Bmi1+ - or Lgr5+-cells clonally expand in human intestine tumors." (PMID 28176811, 2017). "Several PcG proteins such as EZH2 and Bmi1 have been found to play important roles in cancer development and progression, including PCa." (PMID 28029659, 2017). "In brief, Bmi-1 is at an important lynchpin in more than ten different types of cancer, and a wide spectrum of malignancies implicate Bmi-1 as a suitable candidate for predicting outcomes." (PMID 28122538, 2017). "Other target genes of miR-218 that have been identified by previous researchers including BMI1, LAMB3, and LASP1 and the expressions of these genes were associated with the invasion or prognosis in different cancer types." (PMID 28298809, 2017). "Ectopic Bmi1 overexpression results in senescence bypass and immortalization of normal keratinocytes and malignant progression of precancerous lesions into cancers." (PMID 29200967, 2017). "Bmi1 controls important stages in cancer progression including invasion and metastasis by modulating epithelial-mesenchymal transition (EMT) and drug resistance." (PMID 28418883, 2017). "The number of Bmi1-positive cancer cells in PTC-209-treated samples was significantly less than those in vehicle-treated samples, therefore suggesting that Bmi1 was inhibited in vivo by PTC-209." (PMID 29200967, 2017). "Further, Bmi1 has been identified as an important transcription factor supporting the transformation of cancer stem cells in a variety of tumors." (PMID 29262534, 2017). "Mounting evidence has established that Bmi1 is a key oncogene intricately linked to cell transformation, EMT and CSCs propagation in diverse cancer contexts including HNSCC." (PMID 29200967, 2017). "Numerous studies have shown that BMI1 promotes cancer cell growth and migration/invasion, but inhibits apoptosis." (PMID 28079973, 2017). "This is conceivable and in agreement with previous findings Bmi1 protein is relatively unstable and has short half-life in cancer cells." (PMID 29200967, 2017). "Recently, BMI-1 was shown to upregulate the multidrug resistance protein 1 (MDR1) upon cisplatin treatment of cells from different types of cancer." (PMID 28968963, 2017). "miR-15a, miR-16 are hence potentially, a new class of cancer biomarkers which can regulate BMI1 expression and hence targeting them can be a better therapeutic approach for human cancer incoming future." (PMID 28655885, 2017). "In the present study, we demonstrated the role of Bmi1 in the miR-218-mediated inhibition of cancer stemness and invasiveness." (PMID 27926533, 2017).